TNF (tumor necrosis factor)
Diseases named in the same sentence as TNF in open-access papers (continued):
Sharing a sentence is not in itself a finding about the gene and the disease.
viral infection (continued). "The differential genes such as KITLG, FOXP3, miR-451, IL-2, IL-10, IL-6, and TNF-α are mainly involved in viral infection and the immune-inflammatory responses." (PMID 34867371, 2021). "Tumour necrosis factor (TNF) is an inflammatory cytokine produced in response to viral infections that promotes the recruitment and activation of leukocytes to sites of infection." (PMID 34451529, 2021). "One subject, who was found to have had a concurrent systemic viral infection, had an increase in IL-1β, IL-6, IL-10, and TNF-α following chDAB4 incubation which appeared to be inversely proportion to chDAB4 concentration used." (PMID 34231102, 2021). "ALI and ARDS are characterized by overproduction of pro-inflammatory cytokines such as IL-1β, TNF-α, and IL-6 as a result of bacterial or viral infection, trauma, excess exposure to oxygen and noxious gases." (PMID 33806560, 2021). "Such an acute severe immunological response in similar viral infections is known to release a cascade of inflammatory mediators, including various interleukins, tumor necrosis factor (TNF α) and other chemokines." (PMID 33390833, 2021). "One of the main physiological roles of TNF is the mediation of acute inflammation during virus infection." (PMID 34451529, 2021). "The severity of these viral infections were positively correlated with the levels of IL-17 and other T-helpers 17 cell-related proinflammatory cytokines, such as IL-1, IL-6, IL-15, TNF, and IFN-γ." (PMID 33802042, 2021). "The relative importance of TNF versus other other cytokines likely varies between different types and stages of viral infection and merits further investigation using in vivo experimental models." (PMID 34016976, 2021). "While these and other studies have shown that TNF-α contributes to the cardiac pathology that results from viral infection, TNF-α knockout (KO) mice have reduced viral clearance and higher mortality following infection." (PMID 34696354, 2021). "CXCL8 expression can be stimulated by interleukin (IL) 6, TNFα, hypoxia and viral infection in cells such as monocytes, neutrophils, epithelial cells and fibroblasts." (PMID 33345622, 2021). "In another study, TNF-α was shown to play a crucial role in the maturation of DC after adenovirus challenge and the activation of adaptive immunity in response to viral infection." (PMID 32882823, 2020). "IFN-γ intervenes in macrophage activation, induces the expression of MHC class II molecules, increases cytotoxic potential and favours, together with TNF-α, the development of the fundamental Th1 cell responses to control viral infections." (PMID 33138803, 2020). "Serum levels of interleukin-6, interleukin-8, tumor necrosis factor-α, interferon gamma, and granulocyte colony stimulating factor increase following viral infection." (PMID 33425271, 2020). "Multifunctional T cells, simultaneously secreting IL-2, TNF-α, and IFN-γ, have been associated with the control of numerous viral infections, including HCV." (PMID 33343515, 2020). "The viral infection-related regulatory cytokines (IL-1beta) or tumor necrosis factor and many genes in Th1 and Th2 differentiation pathways were upregulated in the high immune score group and played an important role in host-pathogen interaction." (PMID 32509861, 2020). "Necroptosis can be stimulated by TNF, other members of the TNF death ligand family, interferons, Toll-like receptor signaling and viral infection." (PMID 32182899, 2020). "Chloroquine is also immunomodulatory, capable of suppressing the production and release of factors which mediate the inflammatory complications of viral diseases (tumor necrosis factor and interleukin 6)." (PMID 32110875, 2020). "Studies have demonstrated that the buildup of CQ and HCQ in lymphocytes as well as macrophages resulted in anti-inflammatory activities in diverse viral diseases depicted with the overproduction of tumor necrosis factor-α (TNF-α) by the alveolar macrophages." (PMID 33062720, 2020).
viral infection (continued). "Viral infections trigger the production of pro-inflammatory cytokines, particularly IL-1β and TNF-α, in human pancreatic cells through a TLR4-dependent pathway." (PMID 33071971, 2020). "Our study highlights a distinct TNF response and extrinsic apoptotic signaling exists in different cell types, a finding that is likely to influence inflammatory signaling during other viral infections or inflammatory diseases." (PMID 33126536, 2020). "PCT synthesis is stimulated by cytokines such as IL-6, IL-1β, and TNF-α, or directly by lipopolysaccharides and it is downregulated by interferon-γ, which is commonly produced in response to viral infections." (PMID 33419284, 2020). "IFNs synergize with TNF to disrupt development or to mediate tissue damage during endotoxemia, hepatitis, as well as viral infections." (PMID 33126536, 2020). "Tumor necrosis factor (TNF) is one among the key cytokines that mediate the immune system to protecthumans against viral infections." (PMID 33659804, 2020). "CASP3 is a critical caspase in the down-stream of apoptosis pathways that is activated by eternal and external signals such as virus infection, death receptor ligands (TNF, TRAIL, etc.)and cell-mediated cytotoxicity." (PMID 32637426, 2020). "TNF-α is a pleiotropic cytokine that mediates host response to infections and play decisive roles in the outcome of a number of viral infections, contributing to virus control or immune mediated pathology." (PMID 33072088, 2020). "Viral infection is marked by the activation of immune system, which is evident from the enrichment of several pathways, including IL-17, TNF, and apoptosis signaling pathways among others." (PMID 33521069, 2020). "These genes are mostly related to the IL-17 signaling pathway, the TNF signaling pathway, and the host response against viral infection." (PMID 33301474, 2020). "In particular, chloroquine (CQ) and its less toxic metabolite hydroxychloroquine (HCQ), affect the release of tumor necrosis factor-alpha (TNF-α), IL-1 and IL-6 in viral infections by flaviviruses, retroviruses, and coronaviruses." (PMID 33203141, 2020). "The downregulation of IFN-β and TNF-α expression is also observed in ADE of ross river virus infection or PRRSV infection." (PMID 32046249, 2020). "Thiopurines were related to a risk of serious viral infection in IBD patients, while a meta-analysis revealed that anti-tumor necrosis factor therapy was associated developing an opportunistic infection." (PMID 32765952, 2020). "IRF upregulation induced by Type I and II Interferons, viral infection, LPS in addition to several cytokines including TNF-a, IL-1β, IL6 and IL23." (PMID 33137133, 2020). "This occurs through the increased expression of cytokines, such as IFNγ (Interferon gamma) and TNFα (Tumor necrosis factor alpha), which are typically protective in the context of bacterial and viral infection." (PMID 32708830, 2020). "First, Type II alveolar cells will secrete a host of inflammatory cytokines in response to viral infection such as IL-1β, IL-6, TNF-α, CXCL10, and CCL2 that will act to recruit other inflammatory cells to help abate the viral infection." (PMID 32760409, 2020). "Induction of proinflammatory cytokines such as IL-1β, IL-6, IFN-α, and TNF-α, is indicative of acute viral infection in animals." (PMID 31906555, 2020). "The tumor necrosis factor alpha (TNFα) is primarily engaged in host’s defense against bacterial and viral infection." (PMID 33585180, 2020). "The expression of IL-6 was mainly induced by interleukin-1α, tumor necrosis factor (TNF)-α and other stimuli including virus infections, bacterial products and factors secreted by necrotic cells." (PMID 33195318, 2020). "In viral infections, TNFα can induce pro-inflammatory cytokine production and activate TNF-dependent pathways." (PMID 33200027, 2020).
viral infection (continued). "Both cell types have been shown to contribute to inflammation following viral infection by producing cytokines such as TNFα and inducible nitrous oxide synthase." (PMID 31842327, 2019). "However, multiple adverse effects of TNF-α inhibition have been identified, including a two-to four-fold increased risk of active tuberculosis and other granulomatous conditions and an increased occurrence of some other serious bacterial, fungal and certain viral infections." (PMID 30732563, 2019). "TNF-α also regulates complex inflammatory and immune response during viral infection, including activation and aggregation of cytotoxic T lymphocytes, neutrophils, natural killer cells, and macrophages." (PMID 31288442, 2019). "The release of cytokines such as IFN-β, TNF-α, and IL-6 during viral infections plays a crucial role in the innate immune response against viruses." (PMID 31213553, 2019). "Inhibitors of IL8 and targeting IL12, IL2, interferon-gamma (IFNγ) and tumor necrosis factor-α (TNF-α) are other possible immune-modulators used to combat some viral infections." (PMID 31787892, 2019). "Many studies showed that IL-2, IFN-γ, and TNF-α are involved in the elimination of viral infection through modulating Th1 pattern and inflammatory responses." (PMID 31749917, 2019). "Necroptosis is a form of regulated cell death, which can be initiated by a variety of triggers, including TNF, interferon, bacterial lipopolysaccharide, dsRNA, viral infection and anti-cancer drugs." (PMID 31026281, 2019). "The lncRNAs THRIL, NeST, NEAT, and lincRNA-Cox2 can participate in immune responses against viral infection mainly through regulating the expression of TNF-α, IFN-γ, IL8, and inflammatory response, respectively." (PMID 32063887, 2019). "TNF-α is a pleiotropic pro-inflammatory cytokine, which has been shown to play critical roles in the pathogeneses of several diseases, including viral infections." (PMID 31333667, 2019). "Ma found that miRNA-29 family members control the immune system and host–pathogen interactions and influence cytokine (IFN, TNF, and interleukin) signaling in response to bacterial and viral infections." (PMID 31779082, 2019). "TNF triggers the maintenance of CD169+ cells during viral infection to protect animals against the development of severe disease." (PMID 29142134, 2018). "Alteration of the immune response to infections is less pronounced with ETA than with IFX and ADA but control of bacterial and viral infections is decreased by anti-TNF, and assessment of the infection and vaccine status is required." (PMID 30314507, 2018). "iRhom2 knockout mice are broadly healthy, beyond defects in TNFα and type I interferon signalling that are only apparent upon challenge by bacterial and viral infections." (PMID 29897336, 2018). "On the other hand, TNF-α induced by viral infection promotes cytolysis in fibrosarcoma cells implying that, upon different stimuli, TNF-α induces apoptosis." (PMID 30166456, 2018). "During viral infection, inhibition of miR-451 expression elevates secretion of IL-6 and TNF-α in three types of primary dendritic cells." (PMID 29652844, 2018). "Membrane‐bound TNF‐α has been used as a marker for detection of antigen‐specific CD8+ T cells in human viral infections." (PMID 28967229, 2018). "In summary, these findings indicate that TNF delivers a survival signal that is important for the maintenance of CD169+ cells in the spleen after viral infection and for IFN-I production." (PMID 29142134, 2018). "It is well established that innate factors, including IFN-α, IFN-γ, TNF-α and IL-12, play a critical role in inhibiting virus infections; thus, the levels of these cytokines are critical for antiviral immunity." (PMID 30150559, 2018). "Targeting specific epigenetic mechanisms that influence expression of TNFα, NF-κB1a, IFNβ, and IL-12b and IL-6 provides a potential advantage during virus infection." (PMID 30483224, 2018).
viral infection (continued). "Meanwhile, B4GALT5 up-regulated the expression of IFN-α and inflammatory factors (IL6, IL-18, IL-1β, TNF-α) to resist viral infection." (PMID 29546034, 2018). "The advent of anti-TNF-α antibodies has revolutionized the treatment of IBD, but some reports suggest an increased risk of malignancy and other bacterial or viral infections." (PMID 29862296, 2018). "TNF and chemokines are important in the development of human pathologies unrelated to viral infection." (PMID 29724993, 2018). "To examine the impact of viral infection on IκBα degradation, we further treated infected cells with TNF-α for different time periods at 14 hours post-infection, which is expected to induce a sustained reduction in IκBα levels." (PMID 29370303, 2018). "Necroptosis is morphologically similar to necrosis and can be induced by virus infection, or death ligands including tumor necrosis factor (TNF), Fas ligand, and TRAIL when caspase activation is blocked." (PMID 30367066, 2018). "Inflammatory cytokine tumor necrosis factor α (TNFα) is a potent activator of host immune responses to viral infections." (PMID 30740112, 2018). "Like IFN responses, with low MOI value, also CXCL10, CCL5, and TNF-α responses were higher in H5N1-infected Mɸs with low MOI value than with low MOI values in H3N2 or H7N9 virus infection." (PMID 30065728, 2018). "Synergistic effects of IL-1β, IL-6 and TNF-α on inflammatory and stress mediators and IL-1β and IL-17 on chronic lung inflammation after viral infection have been reported." (PMID 27714503, 2017). "In the context of a chronic viral infection, TNF induced CD4+ T cell dysfunction, also called T cell exhaustion, through PD-1 up-regulation." (PMID 29273790, 2017). "TNF-α and IFNs are involved in the innate immune response, which is the first line of defense against viral infections." (PMID 28086978, 2017). "After seasonal virus infection, TNF-α levels in asthmatic mice increased to only 92.2 pg/mL at 3 days post-infection, which was similar to the levels in control/A(H1N1)pdm09 mice (p = 0.06), and these levels were maintained until 7 days post-infection." (PMID 28831046, 2017). "In dendritic cells of patients with COPD, OM-85 increased the secretion of IL-1α, IL-1β, IL-6 and TNF-α, which was regarded as a strengthening of the immune response during viral infection." (PMID 29182620, 2017). "LH-C blocked the early stages (0–2 h) of virus infection, it also suppressed virus-induced NF-kB activation and alleviated virus-induced gene expression of IL-6, IL-8, TNF-a, IP-10, and MCP-1 in a dose-dependent manner." (PMID 28235408, 2017). "Instead, the class I IFN priming phenomenon promotes a vigorous response to direct viral infection more than IL-1β or TNF-α provide." (PMID 28289923, 2017). "TBK1 null fibroblasts exhibited normal NF-κB activation in response to tumor necrosis factor α (TNFα), interleukin-1 and virus infection." (PMID 28493975, 2017). "The choice of cytokines was based on the known role of these molecules in the context of neuropathology, either by mediating inflammation (IL-6, IL-1β, TNFα, CCL5, CXCL1) and/or by their association to viral infections (IFNs)." (PMID 28330482, 2017). "For instance, RIPK1 was shown to be essential in inducing inflammatory cytokines (IL-6, IL-1β, TNF-α) in response to bacterial and viral infections." (PMID 28410401, 2017). "Many viral infections stimulate TLR- or TNF-α-mediated signaling, resulting in the activation of the NLRP3 inflammasome and leading to the subsequent production of IL-1β and COX-2." (PMID 28445497, 2017). "Ischemia, injury, bacterial and viral infections, multiple sclerosis and AD increase the expression of TNF-α in brain; in these conditions microglial cells represent the most prominent source of TNF-α." (PMID 28674485, 2017). "Although TNF-α is associated with the aggravation of CVB3-induced myocarditis, it supports IFN signaling during viral infection, which is important for controlling viral replication." (PMID 28973047, 2017).
viral infection (continued). "Virus-induced secretion of cytokines, such as INF, TNF, and IL, contribute to innate immunity against viral infection." (PMID 28417913, 2017). "Failure of cytotoxic CD8+ T cells to control viral infection can lead to severe immune dysregulation and immunopathology due to overproduction of cytokines like TNF-α or IFN-γ (refs 39, 44)." (PMID 28290449, 2017). "These mediators also regulate BBB permeability, especially in response to viral infections: TNF-α increases barrier permeability, while IFN-β decreases it." (PMID 28143979, 2017). "As such, the regulation and role of CD8+ T cell-derived TNF following viral infection is of great interest." (PMID 28886201, 2017). "Together, results indicate that ORFV073 inhibits both virus infection-and TNFα-induced NF-κB-p65 activation by preventing activation of the IKK complex." (PMID 28787456, 2017). "Although a number of cell types are able to produce TNF, the ability of CD8+ T cells to produce TNF following viral infection is a hallmark of their effector function." (PMID 28886201, 2017). "Noteworthy, the cytokines of crucial importance for clearing a viral infection, such as the Th1 cytokines IFNγ, and IL‐15, the pro‐inflammatory cytokines IL‐1β, IL‐6, TNFα, and TNFβ/lymphotoxin, were downregulated." (PMID 28805308, 2017). "The results indicate that IFNγ and TNFα still play important roles to control virus infection in this study." (PMID 29070073, 2017). "Tumor necrosis factor (TNF)-alpha is a powerful cytokine secreted by several cell types after viral infection." (PMID 28798904, 2017). "Tumor necrosis factor-alpha (TNF-α) is a significant activator of host immune responses to viral infections." (PMID 29234324, 2017). "Here, we have used a viral infection model in zebrafish to identify the mechanism of action by which TNFα has a deleterious role for the host to combat certain viral infections." (PMID 27351838, 2016). "Some of the few studies investigating oncolytic herpes simplex virus in Ewing sarcoma have shown virus infection induces TNFα and IFNβ in the tumor microenvironment, which have been shown to synergistically kill Ewing sarcoma cells." (PMID 28536380, 2016). "Both IFN and TNF contribute to the innate immunity against viral infection and TNF triggers multiple antiviral mechanisms and synergizes with IFN in promoting antiviral activities." (PMID 27688789, 2016). "Other components from exosomes that inhibit viral infections are interleukins, interferon-alpha, interferon-beta, and tumor necrosis factor (TNF-α)." (PMID 26981123, 2016). "The high levels of TNF-α and CXCL10 have been linked to the persistent severe viral disease in patients with severe acute respiratory syndrome." (PMID 27867373, 2016). "Activated endothelium can also secrete proinflammatory cytokines and chemokines such as IL-6, MIG/CXCL9, IP-10/CXCL10, type I and type II IFNs, MCP-1/CCL2, and TNF-α in response to a virus infection." (PMID 26965109, 2016). "In summary, these findings indicate that G6PD knockdown impairs TNF-α/MAPK/NF-κB/COX-2 signaling as a result of insufficient NOX activation, leading to the eventual increase in susceptibility to viral infection." (PMID 27097228, 2016). "Interesting, TNFα can also have a dual role in viral infection by promoting cell survival or cell death depending on the expression and activation balance of its receptors." (PMID 27351838, 2016). "Since this is the first study conducted to address the enhancing role of TNFα in viral pathogenesis, we decided to dissect the essential steps occurring during viral infection in order to identify which of them, if any, were affected by TNFα." (PMID 27351838, 2016). "TNFα is a pleiotropic pro-inflammatory cytokine with a key role in the activation of the immune system to fight viral infections." (PMID 27351838, 2016).